ACE (angiotensin I converting enzyme)
Diseases named in the same sentence as ACE in open-access papers (continued):
Sharing a sentence is not in itself a finding about the gene and the disease.
blood pressure (17 papers, 2010 to 2026). "Current therapeutic regimens include angiotensin II receptor blocker (ARB) and inhibitors for angiotensin-converting enzyme (ACE) to reduce the high blood pressure-associated renal complications and progression to DN." (PMID 33959100, 2021). "For instance, one would argue that if high blood pressure occurs for any reason and this might be associated with high expression and/or activity of ACE, hemorphins might be then released to counterbalance this situation in order to avoid any risk of sustained or chronic hypertension." (PMID 31708782, 2019). "ACE inhibitors are generally used to treat high blood pressure and heart problems because these drugs can relax blood vessels by inhibiting ACE in the body and decreasing blood pressure." (PMID 38731893, 2024). "The angiotensin-converting enzyme “ACE” suppressing activity of peptides promotes their use for mitigating high blood pressure." (PMID 35757269, 2022). "BSG has also been found to inhibit the angiotensin-converting enzyme (ACE), suggesting that it may help manage high blood pressure." (PMID 41596886, 2026). "According to the NHANES 2015–16 survey, in adults aged 60–79, the most commonly used prescription drugs were lipid-lowering drugs (45.0%), antidiabetic agents (23.6%), beta-blockers (for high blood pressure or heart disease, 22.3%), ACE inhibitors (21.3%), and proton pump inhibitors (16.9%).." (PMID 35698037, 2022). "Hence, ACE inhibitors, which are widely used to lower high blood pressure, increase bradykinin levels, and, as bradykinin is a major vasodilator, this augments the antihypertensive effect of ACE inhibitors." (PMID 34642664, 2021). "Only two patients in our study received ACE inhibitors for management of high blood pressure and hence background drug therapy is unlikely to have impacted our findings." (PMID 33889599, 2021).
infarction (17 papers, 2012 to 2025). A localised pathological necrosis of tissue resulting from obstruction of the blood supply usually by a thrombus, an embolus, or vascular torsion. "Although no overall significant effects were found in our study, subgroup analyses revealed a significantly higher AMI incidence 3 days after the spring transition for persons with ACE inhibitor medication prior to infarction." (PMID 26271748, 2015). "The MRI-confirmed infarction with MVO guided the initiation of secondary prevention therapy with statins, ACE inhibitors, beta-blockers, and single antiplatelet therapy, while avoiding dual antiplatelet therapy due to bleeding risk." (PMID 40625465, 2025).
injury (17 papers, 2013 to 2025). Damage inflicted on the body as the direct or indirect result of an external force, with or without disruption of structural continuity. "Experimental inflammatory lung injury causes pulmonary endothelial angiotensin-converting enzyme-1 (ACE-1) shedding, which, after transiently increasing systemic angiotensin-II, reduces systemic angiotensin-II levels over time." (PMID 38103056, 2023). "Experimental inflammatory lung injury causes pulmonary endothelial ACE-1 shedding, and pulmonary AT1R signaling may promote ventilator-induced acute lung injury." (PMID 39593182, 2024). "The potential benefits of angiotensin-converting enzyme (ACE) inhibitors and statins in AD prevention have been tested among patients with a history of traumatic brain injury." (PMID 40426605, 2025). "They documented a significant elevation in ACE and Angiotensin II during the acute phase of cholestatic-induced liver injury, followed by a gradual increase in alternative RAS components during the progression of chronic liver damage." (PMID 41170193, 2025). "Unlike relcovaptan, tolvaptan affected the ACE inhibitor pathway, which is linked to increased immune reactivity and worsened neuronal damage through substance P degradation after brain injury, thereby exacerbating neuronal damage and motor deficits." (PMID 41509943, 2025). "Vitamin D regulates the renin–angiotensin–aldosterone system (RAAS), decreasing renin and ACE expression and promoting ACE-2 expression, which may explain the possible protective role against acute lung injury." (PMID 35409648, 2022). "Since zinc toxicity is likely a key component in neuronal death associated with acute brain injury in diverse animal models, the use of BBB-permeable ACE inhibitors or angiotensin II receptor antagonists may provide neuroprotection in some cases of acute brain injury." (PMID 24289788, 2013).
Mitral regurgitation (17 papers, 2007 to 2025). An abnormality of the mitral valve characterized by insufficiency or incompetence of the mitral valve resulting in retrograde leaking of blood through the mitral valve upon ventricular contraction. "In one patient with AMVP and mildly reduced LVEF, the repeat CMR showed disappearance of the grade 1 mitral regurgitation at baseline under therapy with beta-blockers and low-dose ACE-inhibitors." (PMID 38731198, 2024). "One interesting finding was that only 15% of patients with severe mitral regurgitation were receiving ACE inhibitors." (PMID 37181974, 2023). "However, paradoxically, only 20% of the patients with rheumatic mitral regurgitation were on ACE inhibitors or ARBs as noted in our study, which is the cornerstone of therapy in mitral regurgitation." (PMID 37181974, 2023). "ACE inhibitors or ARBs decrease the afterload, decrease the central aortic pressure, and increase the forward flow during systolic ejection so that less amount of blood regurgitates into the left atrium, thereby decreasing the mitral regurgitation." (PMID 37181974, 2023). "Furthermore, in case of mitral regurgitation a reduction of preload with beta-blockers, calcium channel blockers or diuretics can be advantageous, in severe cases vasodilator therapy including ACE inhibitors and angiotensin II receptor blockers may be of benefit." (PMID 17653281, 2007). "Upon repeat CMR she was treated with betablockers and low dose ACE-inhibitors, and no mitral valve regurgitation was noted." (PMID 38731198, 2024).
acquired angioedema (16 papers, 2010 to 2025). Acquired angioedema (AAE) is characterized by the occurrence of transitory and recurrent subcutaneous and/or submucosal edemas resulting in swelling and/or abdominal pain due to an acquired C1 inhibitor (C1-INH) deficiency. "Acquired angioedema (AAE) is most frequently associated with lymphoproliferative and autoimmune disorders and with some medications including ACE inhibitors and plasmin activators." (PMID 20667123, 2010).
respiratory failure (16 papers, 2016 to 2025). The significant impairment of gas exchange within the lungs resulting in hypoxia, hypercarbia, or both, to the extent that organ tissue perfusion is severely compromised. "In patients who developed ARDS compared with other patients in respiratory failure, the D/D deletion of the ACE gene (which is associated with increased expression of ACE) was more prevalent." (PMID 35106954, 2022). "History of prior AKI, use of combination drugs such as ACE inhibitors, NSAIDS and diuretics, and presence of comorbid conditions such as respiratory failure were found significant for both AKI detection and risk prediction." (PMID 27025458, 2016). "Such an effect is biologically plausible in view of the high levels of angiotensin-converting enzyme (ACE) in the pulmonary endothelium, accounting for reduced Ang II levels in patients with acute respiratory failure." (PMID 39685830, 2024).
ST Elevation Myocardial Infarction (16 papers, 2010 to 2025). A myocardial infarction that produces elevation in the ST segments of the ECG. "Clinical comorbidities, such as renaldysfunction, ST-elevation myocardial infarction and bradyarrhythmias, were associated with reduced use of ACE inhibitors, calciumchannel blockers and beta-blockers, respectively." (PMID 40162464, 2024). "Blocking the renin-angiotensin-aldosterone system in ST-elevation myocardial infarction (STEMI) patients prevents heart failure and recurrent thrombosis in particular by the use of angiotensin-converting-enzyme (ACE) inhibitors if there are no contraindications to their use." (PMID 27064499, 2016).
thrombosis (16 papers, 2012 to 2025). "ACE gene shows potent vasoconstrictive effects, attenuation of fibrinolysis, and platelet activation and aggregation, and ACE I/D polymorphism represents a susceptibility risk biomarker for thrombosis." (PMID 36371754, 2023). "Some previous studies have reported an association between the ACE D allele and increased risk of thrombosis." (PMID 27326417, 2016). "This study aimed to analyze the association between PAI-1 4G/5G and ACE I/D gene polymorphisms, and leukocytosis with thrombosis in patients with PV and ET." (PMID 24744648, 2012). "ACE D/D genotype has been suggested as a susceptibility marker of thrombosis." (PMID 33585520, 2020). "It has been shown that vascular endothelial growth factor A (VEGFA) and angiotensin-converting enzyme (ACE) are upregulated in the corpus cavernosum of diabetic rats, and these proteins can promote the generation of mucosal blood vessels and increase the risk of vascular thrombosis." (PMID 36210810, 2022). "Angiotensin converting enzyme (ACE) converts angiotensin I to angiotensin II and is involved in thrombosis." (PMID 27326417, 2016). "Key search terms were: indomethacin, non-steroidal anti-inflammatory drugs, NSAIDs, lisinopril, angiotensin-converting enzyme inhibitors, ACE-Is, hydrochlorothiazide, diuretics, portal vein thrombosis, venous thrombosis and thromboembolism." (PMID 23148576, 2012). "ACE I/D and Apo B R3500Q polymorphisms have also been associated with thrombosis and CVD since they increase the risk of MI and thrombotic episodes, whereas the ACE D/D variant has also been linked to elevated plasma levels of ACE and suppression of fibrinolysis." (PMID 36289926, 2022). "To date, no study on PAI-1 4G/5G and ACE I/D gene polymorphism in relation to the risk of thrombosis in patients with PV and ET has been published." (PMID 24744648, 2012). "The ACE deletion/deletion(D/D)genotype represents a marker of thrombosis in subjects apparently without predisposing factors and/or traditional thrombophilic alterations and increases the risk of venous thromboembolism in subjects in whom a thrombogenic condition occurs." (PMID 34441050, 2021). "Some authors have also shown that the ACE D/D genotype represents a susceptibility marker for thrombosis in subjects apparently without predisposing factors and traditional thrombophilic alterations and increases the risk of venous thromboembolism in subjects in whom a thrombogenic condition occurs." (PMID 34441050, 2021). "In the present study, we have examined the expression levels of two miRNA regulators of the ACE/PAI-1 axis (miR-145-5p and miR-34a-5p) in pediatric patients with thrombosis, 1–18 months post-incident, compared to age- and gender-matched healthy controls." (PMID 41155403, 2025).
Alport syndrome (15 papers, 2012 to 2026). A rare renal disease characterized by glomerular nephropathy with hematuria progressing to end-stage renal disease (ESRD), frequently associated with sensorineural deafness, and occasionally with ocular anomalies. "By enabling the production of full-length, functional protein, ACE-tRNA represents an ideal approach for directly addressing the genetic defect in Alport syndrome due to nonsense variants." (PMID 41417821, 2025). "The detection of Alport syndrome is vital due to the risk it poses to other members of the family and prophylaxis with angiotensin-converting enzyme (ACE) inhibitors, which postpone the commencement of renal impairment." (PMID 38021591, 2023). "Our findings establish a proof of concept for ACE-tRNA–mediated therapy in Alport syndrome and provide a strong rationale for advancing to in vivo studies in the near future." (PMID 41417821, 2025). "At least blood pressure control using ACE inhibitors is highly effective in glomerulonephritis and Alport syndrome." (PMID 27537361, 2016). "This concept is further supported by the observation that reducing mechanical strain in the glomerulus with angiotensin-converting enzyme (ACE) inhibitors, which lower blood pressure as well as transcapillary filtration pressure, significantly delays disease progression in Alport syndrome." (PMID 25352829, 2014). "Under ACE inhibition, both in the minimal change disease and in the “FSGS/IgAN/ GN,” a significant difference in uEGF/uCreat was still seen compared to healthy controls as well as in comparison to Alport syndrome." (PMID 34900856, 2021).
Arthritis (15 papers, 2010 to 2024). Inflammation of a joint. "In particular, this study aimed to investigate the relationship between the development of arthritis and various laboratory parameters, including vitamin D levels, liver enzyme levels, and ACE levels, as well as clinical features and comorbid conditions." (PMID 39768486, 2024). "Serum renin and ACE levels were similar in arthritis patients and in healthy controls in contrast with higher levels in synovial fluid of arthritis patients." (PMID 37878123, 2023). "In the mixed cohort of 51 arthritis (RA+AS) patients, serum ACE concentration significantly increased after 6 M (166.7 ng/mL; p = 0.003) and 12 M of treatment (183.4 ng/mL; p < 0.001) compared to B (142.7 ng/mL)." (PMID 35155468, 2021). "Information regarding regulation of ACE by inflammatory mediators is less; however, in an adjuvant induced arthritis model, the expression of ACE was found to be decreased in heart." (PMID 31333451, 2019). "These included weight, a history of joint pain or arthritis, other long term conditions and some medications (including ACE inhibitors, gastric acid reducers, quinolones, tibolones, and zoledronic acid) have all been monitored in this sample." (PMID 24964929, 2014). "The ACE inhibitor quinapril was shown to reduce experimental arthritis in mice." (PMID 36009795, 2022). "Thus, in treated arthritis patients with lower degree of inflammation, ACE levels may become a marker of remaining systemic inflammation or disease activity." (PMID 35155468, 2021). "With respect to the regulation of ACE and ACE2 production in arthritides, in animal models of arthritis, Ang1−7 exerted significant anti-inflammatory effects as it attenuated oxidative stress, as well as TNF-α, interleukin 1 (IL-1) and IL-6 production." (PMID 35155468, 2021). "Although perindopril treatment has been shown to induce joint protection in CIA rats with increased ACE and AT1 and AT2 receptors, the specific receptor by which Ang II exacerbate arthritis in the joint region is unknown." (PMID 37237567, 2023).
Cirrhosis (15 papers, 2016 to 2025). A chronic disorder of the liver in which liver tissue becomes scarred and is partially replaced by regenerative nodules and fibrotic tissue resulting in loss of liver function. "Nonetheless, as NAFLD advances to stage 4 (cirrhosis), liver transplantation becomes the primary treatment option, despite the use of multiple medications, such as antibiotics, antivirals, beta-blockers, and angiotensin-converting enzyme (ACE) inhibitors, for cirrhosis-associated complications." (PMID 37736923, 2023). "Importantly, ACE negatively correlated with antiplasmin activity in our cirrhosis patients, thus possibly contributing to increased levels of plasmin." (PMID 34945736, 2021). "But ACE-inhibitors and AT1 receptor-antagonists aggravate the arterial hypotension and hyper-reninism of ascitic cirrhosis." (PMID 27637026, 2016). "Similarly, angiotensin-converting enzyme (ACE) inhibitors are not recommended as they can worsen the already present vasodilation characteristic of advanced cirrhosis." (PMID 38817353, 2024). "Therefore, ACE inhibitors or angiotensin receptor blockers are not feasible in patients with advanced cirrhosis." (PMID 38892040, 2024).
Gaucher disease (15 papers, 2009 to 2025). Gaucher disease (GD) is a lysosomal storage disorder encompassing three main forms (types 1, 2 and 3), a fetal form and a variant with cardiac involvement (Gaucher disease - ophthalmoplegia - cardiovascular calcification or Gaucher-like disease). "Known biomarkers of Gaucher-disease activity are platelets, chitotriosidase, angiotensin-converting enzyme (ACE), tartrate-resistant acid phosphatase (TRAP) and ferritin." (PMID 20696071, 2010). "Furthermore, there are numerous other conditions in which high levels of ACE have been found, such as asbestosis, diabetes, Gaucher’s disease, hyperthyroidism, Hodgkin’s lymphoma, lung malignancies, tuberculosis, silicosis, and histoplasmosis." (PMID 39768579, 2024).
glomerular disease (15 papers, 2009 to 2025). "Angiotensin II is an essential contributor to the pathogenesis of the glomerular disease, and it is well known that ACE inhibition and angiotensin type 1 receptor (AT1R) block have antiproteinuric effects." (PMID 35448080, 2022). "There are different podocentric therapeutic options for DN and other glomerulopathies, such as angiotensinconverting enzyme (ACE) inhibitors or angiotensin receptor blockers (ARB), glucocorticoids, CNIs, and even Rituximab." (PMID 34095318, 2021). "RAAS inhibitors (angiotensin-converting enzyme (ACE) inhibitors or angiotensin receptor blockers (ARB)) are used for their antiproteinuric effect in glomerular diseases." (PMID 32713282, 2020). "ACE inhibitors and ARBs exert renoprotective effects in glomerular diseases, mostly by reducing proteinuria." (PMID 30514826, 2019). "Our data suggest that uEGF/uCreat might be a helpful, non-invasive tool to distinguish minimal change disease from other proteinuric glomerular diseases, by linking the percentage of decrease in uEGF/uCreat to its response on ACE inhibition and to the absence of genetic predisposition." (PMID 34900856, 2021). "Fourth, our network analysis did not evaluate concerns about polymorphisms of the ACE gene, or the AT1R gene, which are associated with glomerular disease susceptibility, natural history, and the response to therapy." (PMID 34268008, 2021). "Consistent with guidelines recommending standard treatment in dogs with glomerular disease, all patients with a known medication history were treated with an ACE inhibitor or ARB with or without other concurrent medications." (PMID 33463760, 2020). "RAS blocking agents have been employed for treating glomerulopathy in SCD patients; given the potential hypotensive effects of these drugs, we treated chimeric control and SCD mice (5-months old) with 25 mg/kg/day (gavage) enalapril, an ACE inhibitor, for 5 weeks." (PMID 35113975, 2022).